SRC (SRC proto-oncogene, non-receptor tyrosine kinase)
Diseases named in the same sentence as SRC in open-access papers (continued):
Sharing a sentence is not in itself a finding about the gene and the disease.
tumor (continued). "SRC is overexpressed in NSCLC and promotes tumor growth and proliferation." (PMID 39941857, 2025). "However, the roles of SFKs, particularly SRC and YES1, in fibrosis-driven tumor microenvironment modification are still not well understood." (PMID 39776795, 2025). "SRC plays a multifaceted oncogenic role in CCA by activating key signaling pathways, interacting with FAK in response to HGF to promote proliferation and invasion, forming a metastatic SRC–Hic-5–AKT cascade, and phosphorylating YAP to drive tumor growth and therapy resistance." (PMID 41300430, 2025). "Furthermore, we demonstrated in both BRAFV600E CRC cell line xenograft mouse models and PDXs that dual inhibition of SRC and BRAF synergistically reduced tumor growth compared with single-drug therapy." (PMID 40481178, 2025). "In addition to MAPK, SRC kinases can directly modulate many downstream targets including and c-MYC, related to drug resistance and tumor cell survival." (PMID 40481178, 2025). "The downregulation of p-PI3K and p-AKT confirms suppression of survival signaling, while the inhibition of key oncogenic regulators AKT1, MTOR, HIF1A, SRC, and ESR1 suggests broader effects on tumor metabolism, hypoxia adaptation, and growth factor receptor pathways." (PMID 40746726, 2025). "SRC expression was significantly upregulated in tumor tissues compared to matched non-tumorous tissues (paired Student’s t-test, p < 0.001)." (PMID 40650282, 2025). "The PPI network analysis, informed by topological parameters, suggested that PIK3R1, SRC, AR, and MMP9 could be considered as key target genes for the combined anti‐tumor immunity effects of Danggui and Huangqi." (PMID 38863309, 2024). "We found that SRC inhibition alone or combined with anti-BRAF treatment with or without anti-EGFR did not affect the tumor growth in our resistant models (data not shown)." (PMID 39436710, 2024). "The activity of SRC is significantly reduced in tumor cells lacking PTPRE and restoring SRC activity revealed that it is only its reduced activity that caused aberrant proliferation rates of tumor cells lacking PTPRE." (PMID 38674157, 2024). "CASP3, SRC, ESR1, JAK2, PRKACA, HSPA8 and CAT exhibited stronger interactions with other factors, suggesting that they may be the key targets for tumor treatment." (PMID 38675723, 2024). "An unbiased drug screen identified the tyrosine kinase inhibitor dasatinib that potentiates MRTX849 efficacy by inhibiting SRC-dependent JUN activation, avoiding multidrug resistance and tumor suppression in vitro as well as in suitable preclinical mouse models and patient-derived organoids." (PMID 39661665, 2024). "Moreover, we also performed the limiting dilution assay using the SRC stable knockdown CAL51 cells, to evaluate the tumor-initiating frequency in vivo." (PMID 36633714, 2023). "Furthermore, co-upregulations of SRC and YAP1-KLF5 module in TNBC tissues were positively correlated with the tumor malignance." (PMID 36633714, 2023). "CCK-8 and xenograft assay results showed that disruption of this module in SRC-activated TNBC cells could potentially inhibit the hyperproliferation in vitro and the tumor overgrowth in vivo." (PMID 36633714, 2023). "Consistent trends were observed with SRC amplifications in PFS (p = 0.10, HR = 0.69 [0.44–1.07], median PFS wild-type tumours 9.6 months vs mutants 11.1 months) and ORR (p = 0.18, OR = 0.45 [0.14–1.45], ratio ORR wild-type 0.66 vs mutant tumours 0.83)." (PMID 37666855, 2023). "In contrast, drugs with molecular targets: ABL, KIT, PDGF, SRC, and VEGFR were enriched in the drug clusters showing a strong effect on tumor cell intravasation with less impact on cell invasion or cell proliferation, of which, Imatinib, a multi-kinase inhibitor targeting BCR-ABL/PDGFR/KIT." (PMID 38239643, 2023).
tumor (continued). "Both the FOXM1 inhibitor NB-55 and the SFKi eCF506 also significantly impaired the growth of a second PDX model established from a luminal B–like tumor, suppressed the expression of FOXM1 and its targets, including SRC, and significantly reduced lung metastasis in this model." (PMID 36795481, 2023). "The role of PDGF-Rβ in SRC activation and THY1-mediated suppression of tumor invasion was examined." (PMID 37046850, 2023). "In support of this, SRC activation was strongly correlated with the PC1 and EMT signatures and the EMT genes (e.g. ZEB2, TWIST1) that are known to promote migration, invasion and metastasis and to induce tumor cells to acquire stem cell characteristics." (PMID 35272617, 2022). "Specifically, SRC kinase-mediated NF-κB activation is required for CTGF-induced Glut3 expression and the aggressive phenotypes of TNBC, while SRC-mediated ETS1 phosphorylation can stabilize ETS1 and promote anchorage-independent growth in vitro and tumor growth in vivo." (PMID 36581908, 2022). "The Src family kinase c-SRC, a non-receptor-type tyrosine kinase, plays a critical role in tumor progression and metastasis." (PMID 35906197, 2022). "SIRT2 could deacetylate IDH1 at K224 and exhibit a tumor suppression function in a colon cancer cell model by inhibiting IDH1 enzymatic activity and the hypoxia-inducible factor 1α (HIF1α)-SRC transcription axis." (PMID 36577755, 2022). "AZD0424 did not affect the growth of HCC1954 tumour xenografts even though SRC was effectively inhibited using daily dosing of mice with concentrations of ≥ 10 mg·kg−1." (PMID 34856074, 2022). "This suggests that the NCIH747 cell line could respond to tyrosine kinase inhibitors (TKIs) prescribed by Beyondcell for these tumour types such as EGFRi and also to inhibitors to target members from MAPK pathway (MEK and SRC)." (PMID 34911571, 2021). "We speculate that Shan Ci Gu may play a role in inhibiting tumor cell proliferation by targeting several proteins such as EGFR, SRC, and ESR1 in NSCLC." (PMID 34178945, 2021). "SRC is a non-receptor tyrosine kinase responsible for tumor cell apoptosis, migration, and transformation." (PMID 35198564, 2021). "This is possibly due to the tumor-promoting roles of other serotonin receptors, such as HTR1D 42 and HTR7 43, that are slightly upregulated in OC and can activate the SRC signaling." (PMID 34093864, 2021). "Our study also demonstrated that SRC, as the key biomarker for better prognosis, may inversely It is increasingly proven that the immune response to ICT is affected by immune cells and tumour-related factors." (PMID 33830879, 2021). "Despite the increase in phospho-SRC signal in DEXA treated tumours, we did not detect a significant increase in BCL2L1 and MCL1 expression." (PMID 33478100, 2021). "Several oncogenes, like MYC, SRC, and VEGF, harbor complex structures in their 5′UTR, such as G-quadruplexes structures or IRES elements, enhancing their translation in specific situations like tumor development." (PMID 33078202, 2021). "Interestingly, Src42A/SRC is able to activate Yki/YAP, thus forming a feedforward loop to drive tumor progression." (PMID 34862372, 2021). "In particular, the characterization of SRC signaling, could lead to the identification of novel druggable targets to interfere with SRC’s ability to sustain the TME, and therefore ameliorate a tumor’s response to therapy." (PMID 32545574, 2020). "SRC and FAK can also induce the expression and activation of the secreted matrix metalloproteinases MMP2 and MMP9, which are responsible for the ECM remodeling required for tumor invasion." (PMID 32664483, 2020).
tumor (continued). "HGF/MET signaling can stimulate various downstream signaling pathways in tumor cells, such as PI3K/AKT, JAK/STAT, Ras/MAPK, SRC, and Wnt/β-catenin, and it can enhance tumor malignancy by inducing biological processes such as tumor proliferation, invasion, and metastasis." (PMID 33066121, 2020). "Moreover, it has been demonstrated that SRC can modulate TME dynamism also orchestrating movement and infiltration of immune cells into tumor." (PMID 32545574, 2020). "Some of these proteins were tumor suppressors, including Rb, FOXO3, and p27, and many proteins were kinases and involved in the regulation of cell proliferation, differentiation, and apoptosis, such as c-KIT, AKT, EGFR, MAPK1/3, PRKCA, SRC, ACVRL1, and JNK2." (PMID 32917965, 2020). "Levels of FRK, DDR1 and SRC expression on both mRNA and protein level were significantly higher in metastatic patient samples regardless of the tumor stage, while expression levels of SIK2 correlated with tumor size." (PMID 32082487, 2020). "Thus, inhibition of SRC, which significantly decreases YAP/TAZ activity, reduces tumor growth and metastasis." (PMID 30559289, 2019). "SRC proteins, which belong to the non-receptor tyrosine kinase family, promote mitosis in tumor cells during tumorigenesis and tumor development, and increase their adhesion and invasion capacity." (PMID 31354472, 2019). "Moreover, loss of the adenomatous polyposis coli (APC) tumour suppressor in mice results in GP130 upregulation, inducing SRC/YAP and JAK/STAT3 pathways that are needed for tumour formation." (PMID 31091767, 2019). "Together these data reinforce a major role for SRC favoring tumor invasion and metastasis rather than sustaining tumor growth, in good agreement with the presented results herein." (PMID 31731442, 2019). "SRC knockdown also led to a roughly 50% reduction in primary tumor size, but this difference was not quite statistically significant." (PMID 30559289, 2019). "These cell lines stem from disparate tumor or tissue types, but they were all predicted to have very high recruitment of CRKL (more than one copy of CRKL bound to each molecule of IGF1R) coupled with moderately high recruitment of either SRC, SHC1, or RASA1." (PMID 30653502, 2019). "It will be interesting to determine whether any of these drivers of SRC activation also lead to aberrant YAP/TAZ activity and, if so, whether blocking these cues can prevent YAP/TAZ-mediated tumor growth and metastasis." (PMID 30559289, 2019). "Moreover, SLAP displays a prominent tumour suppressive function in human colonic epithelial cells by controlling essential SRC tumour-promoting activities described in CRC, including tumour cell growth and migration." (PMID 31091767, 2019). "Through a gene-silencing approach, we have previously demonstrated that inhibition of SRC in tumor cells, but not in fibroblasts, is essential for the effect observed with pharmacological inhibition of SRC in the co-culture setting." (PMID 30065926, 2018). "CD45 is shown to regulate phosphorylation of kinases such as SRC and JAK family kinases and might have a tumor suppressor role in T-ALL." (PMID 29416774, 2018). "Most of the downregulated genes, including SRC, TGFB1, MMP9 are known to promote tumor metastasis." (PMID 28977939, 2017). "Network analysis of downstream gene signatures revealed several hub genes such as SRC and DNM1L etc. which may mediating tumor promoting functions of CEACAM6." (PMID 29137373, 2017). "Inhibition of ERBB3 signaling via both blockade of SRC and ERBB1 results in tumor cell death." (PMID 26934000, 2016). "Furthermore, both PDXs and the original tumors exhibited conserved genomic DNA alterations including both EGFR amplification and PTEN deletion as well as EGFR, p-EGFR, PTEN, p-SRC, and p-AKT expression correlating with that of the parental tumor." (PMID 27438149, 2016).
tumor (continued). "Dasatinib may be useful as a dual TGF-β/SRC inhibitor in experimental and clinical therapeutics to prevent metastatic spread in late-stage PDAC and other tumours." (PMID 26588899, 2015). "Interestingly, the levels of SRC and PPARB/D expression were highly and significantly correlated in these tumours, as were the expression levels of PPARB/D andTGFB1 and MMP19, respectively, and to a lesser extent, MMP2, VEGFA, VIM and SNAI1." (PMID 24203162, 2014). "Therefore, RTK-induced SRC activity drives aspects of RTK signaling important in tumor progression, and the identification of RTK-induced SRC substrates will offer further insight into the role of SRC in tumorigenesis." (PMID 21049007, 2010). "Similarly, in the other two human NSCLC cell lines (H1299 and H1703), GH and pegvisomant treatments did not alter the phosphorylation status of SRC, which is consistent with tumor samples of NSCLC patients." (PMID 41515995, 2025). "Moreover, the dual inhibition strategy downregulated pEGFR and p-ERK protein levels, demonstrating an effective suppression of SRC and MAPK pathways that could be responsible for the observed inhibition of tumor growth." (PMID 40481178, 2025). "In xenograft tumors, querying GH downstream intracellular signaling intermediates predicted from PDAC patient tumor analysis show that GHRA-treated groups have significant and consistent reductions in the phosphorylation states of STAT5, STAT3, as well as SRC and AKT in both male and female mice." (PMID 39000545, 2024). "We hypothesise that SRC hyperactivity (and consequently increased Slug and Snail stability) could improve TNBC cells’ capacities to survive during the high rates of DNA damage that occur during tumor development, as well as following chemotherapy treatments." (PMID 39327614, 2024). "Moreover, SRC facilitates the activation of ARHGEF5, leading to cell invasion and tumour growth." (PMID 37439249, 2023). "SRC is a member of the non-receptor tyrosine kinase family (Src Family Kinases, SFKs) and plays a critical role in cell adhesion, invasion, proliferation, survival, and angiogenesis during tumor development." (PMID 36902280, 2023). "The activation of SRC following MEK pathway inhibition was strongest in HCT116 cells in vitro, and this was also observed in vivo correlating with enhanced inhibition of HCT116 tumour growth upon trametinib and AZD0424 combination treatment relative to respective single‐agent treatment in vivo." (PMID 34856074, 2022). "It is therefore becoming evident that preclinical models are failing to predict SRC inhibitor clinical efficacy, most likely because tumour cells are not solely dependent on SRC activity for survival and they can switch to other models of survival and growth signalling." (PMID 34856074, 2022). "SRC, a nonreceptor protein tyrosine kinase, participates in the regulation of cell growth and embryonic development and promotes survival, angiogenesis, proliferation and invasion pathways while being activated or overexpressed during tumor development." (PMID 33921111, 2021). "SRC is a non-receptor tyrosine kinase family member with a crucial role in tumor progression." (PMID 33712015, 2021). "Furthermore, APC (p < 0.0001), ASXL1 (p < 0.0001), DNMT3B (p = 0.001), PARP4 (p = 0.002), MET (p = 0.01), TOP1 (p = 0.01), KDR (p = 0.01), SRC (p = 0.01), PAK1 (p = 0.015), ALK (p = 0.02), and MYC (p = 0.03) alterations were found to be more common in tumor samples from AO mCRC patients." (PMID 33194656, 2020). "Interestingly, the hyperactivation of SRC in GBM significantly contributes to sustain the rewiring of some of the main networks, including inflammation and metabolism, which contributes to the establishment of TME and tumor development." (PMID 32545574, 2020).
tumor (continued). "When tested against 16 protein kinases involved in the regulation of tumor growth and metastasis, P03F03 inhibited anaplastic lymphoma kinase (ALK), focal adhesion kinase (FAK), insulin like growth factor (IGF11-R), proto-oncogene SRC, and vascular endothelial growth factor (VEGF-R2 R2)." (PMID 31491907, 2019). "Therefore, we next sought to determine whether SRC-dependent activation of YAP and TAZ is important for tumor growth and metastases." (PMID 30559289, 2019). "Although several SFK inhibitors have been developed, clinical trials in CRC have produced disappointing results probably because of the absence of selection of patients with SRC-dependent tumours and/or the drug’s inability to efficiently target SRC signalling." (PMID 31091767, 2019). "It is not known whether SLAP targets additional SRC oncogenic substrates to mediate its tumor suppressive activity." (PMID 26788993, 2016). "Hence, dasatinib may be useful as a dual TGF-β/SRC inhibitor in experimental and clinical therapeutics to prevent metastatic spread in late-stage PDAC and other tumours." (PMID 26588899, 2015). "The observation that dasatinib is also known to target c-SRC raises the possibility that inhibition of a key negative regulatory element of SRC proteins may be responsible for the lack of dasatinib sensitivity to tumor cells over expressing c-SRC." (PMID 23056181, 2012). "Indeed, the activation of EGFR produces the detachment by SRC-mediated phosphorylation of the p120/E-CAD complex from the low-density lipoprotein receptor-related protein 5/6 (LRP5/6), which together with the frizzled receptors (FZD), activates the Wnt signalosome favoring the tumor cell growth." (PMID 35267574, 2022). "Furthermore, significantly higher SRC expression levels (together with higher CAV1 phosphorylation levels) were present in the malignant epithelial cells of advanced PCa tumors of higher Gleason grades, whereas immunoreactivities of both proteins were declined within the more reactive tumor stroma." (PMID 35155239, 2022). "Thus, RT induced phenotypic and metabolic alterations in stromal fibroblasts caused an activated fibroblast phenotype that was associated with an increased metabolic potential enabling adjacent tumor cell support, effects that were not affected, or particularly limited upon SRC inhibition." (PMID 35155239, 2022). "Likewise, the lack of effectiveness could reflect the involvement of SRC in the first steps of the metastatic cascade to facilitate the migration and invasion of tumor cells, but not in the late stage when tumors are already disseminated." (PMID 31731442, 2019). "We found that SRC and YES1 were significantly upregulated in tumor tissues compared to adjacent non-tumoral liver tissues (p < 0.001), confirming their relevance as therapeutic targets in this study." (PMID 40650282, 2025). "Interference of GDF15 (siRNA or N70Q dominant negative) or EGFR pathway (inhibitor or siRNA for EGFR, SRC or ERK) decreases the resistant-cell survival in culture and tumor growth in mice." (PMID 35853851, 2022). "The lack of pY418 phosphorylated c-SRC and the decrease in expression in disease shown here, indicate that c-SRC does not drive CRC tumor cell proliferation." (PMID 27562229, 2016). "As AZD0424 did not sensitise DLD1 tumours that were inherently resistant to MEK inhibitor treatment, we next asked whether SRC inhibition could (re)sensitise cells that had acquired resistance to MEK inhibitors following prolonged treatment with trametinib." (PMID 34856074, 2022). "SRC and LYN partial methylation in non-neoplastic samples was more frequently observed in individuals presenting tumor samples with hypomethylation of this gene compared with tumors with partial methylation (p < 0.001, for both analyses) or hypermethylation (p < 0.001, for both analyses)." (PMID 26460485, 2015).